U3 (Small nucleolar RNA U3 )
Synonyms: LOC124901505
Gene: Small nucleolar RNA gene on chromosome 6 (92,119,423 to 92,119,633, forward strand). Ensembl gene ENSG00000200492.
Gene Ontology:
Biological process: RNA processing
Cellular component: nucleolus
Homologues: Orthologues: chimpanzee U3 (99% identical), macaque U3 (94% identical), pig U3 (35% identical). Paralogues in human: SNORD3P1 (80% identical), SNORD3E (79% identical), U3 (78% identical), U3 (77% identical), U3 (76% identical), U3 (75% identical), U3 (74% identical), SNORD3H (73% identical), U3 (73% identical), SNORD3D (73% identical), SNORD3G (73% identical), U3 (72% identical), and 13 more.